RUNX3 (RUNX family transcription factor 3)
Diseases named in the same sentence as RUNX3 in open-access papers (continued):
Sharing a sentence is not in itself a finding about the gene and the disease.
tumor (continued). "In bladder cancer, tumor-suppressor genes such as RASSF1A, RUNX3, CDH13, and HOXA9 have been reported to undergo promoter hypermethylation, resulting in loss of tumor-inhibitory function." (PMID 41377897, 2025). "For instance, the tumor suppressor RUNX3 inhibits tumor growth by promoting the degradation of oncogenic proteins through the ubiquitin-proteasome system." (PMID 40299524, 2025). "Runt-related transcription factor 3 (Runx3) is a transcription factor involved in cellular development, inflammatory responses, and tumor suppression." (PMID 41479900, 2025). "RUNX3 is a multifunctional tumour suppressor gene located in chromosome 1p36-35, playing an important regulatory function in the essential processes of cell reproduction, differentiation, and apoptosis." (PMID 40559899, 2025). "A key finding in this study was the up-regulation of RUNX3 (8.81), a runt-related transcription factor with tumor-suppressive roles in multiple cancers." (PMID 40430278, 2025). "The tumor suppressor RUNX3 can bind with GLI1 and promote its ubiquitination, thus resulting in an inversely expression of RUNX3 and GLI1." (PMID 41346572, 2025). "One of the genes, RUNX3 has been associated with CD8 lineage and tumor suppression in MF, but somewhat unexpectedly, here, the expression was highly up-regulated at progression." (PMID 39857770, 2025). "This study aimed to uncover tumor microenvironment (TME) changes in NSCLC with varying RUNX3 expression statuses through single-cell RNA sequencing." (PMID 40916017, 2025). "For example, 4 EWS DMPs were located in RUNX3, a well-recognized tumor suppressor of gastric, colon and many other forms of solid tumors." (PMID 38466776, 2024). "We next examined the in vivo activities of RUNX3 in tumor development and metastasis by subcutaneous and splenic inoculation of HGC-27 cells into NSG mice." (PMID 38240752, 2024). "In pathological settings, RUNX3 enhances CD8+ tumor-infiltrating lymphocytes (TIL) in melanoma, which results in tumor growth inhibition." (PMID 38632596, 2024). "In the present study, we have demonstrated that MEX3C is upregulated in LUAD tumor tissue whereas RUNX3 is downregulated." (PMID 38424632, 2024). "In cutaneous melanoma, RUNX3 acts as a tumor suppressor, with its expression being significantly downregulated in both primary and metastatic tumors." (PMID 38430423, 2024). "RUNX3 engages in intricate regulatory mechanisms governing tumor stemness, generally aligning with the prevailing notion that it serves as a suppressive modulator." (PMID 38430423, 2024). "RUNX3, predominantly recognized as a tumor suppressor, serves as a crucial prognostic marker, with its downregulation often indicative of adverse prognoses." (PMID 38430423, 2024). "In a model using murine P14 T cells targeting GP33-expressing B16 melanoma, overexpression of RUNX3 drove greater abundance of TILs, granzyme B expression, and tissue-residency gene modules to ultimately delay tumour growth and prolong survival." (PMID 39399500, 2024). "Cumulatively, these findings underscore RUNX3's predominant function as a tumor suppressor, consistently found to be downregulated in diverse cancer types." (PMID 38430423, 2024). "Overall, RUNX3 predominantly acts as a dampener of tumor stemness, distinguishing it from RUNX1 and RUNX2." (PMID 38430423, 2024). "RUNX3 pathway signature was elevated in tumor tissues compared with non-tumor tissues, in the TCGA-KIRC cohort (P < 0.001)." (PMID 38172737, 2024). "In various cancer cell types, RUNX3 is inactivated due to epigenetic silencing and cytoplasmic localization from the nucleus to the cytoplasm, thereby losing its function as a tumor suppressor." (PMID 38683453, 2024). "The RUNX3 pathway act as a major regulator of tumor progression and metastasis, hence influencing patients’ survival." (PMID 38172737, 2024). "Emphasis is placed on RUNX3, widely acknowledged as a tumor suppressor, and the implications of its downregulation in selected cancer types." (PMID 38430423, 2024).
tumor (continued). "As highlighted previously, transcription factors such as RUNX3 can be targeted to drive accumulation of T cells in tumour sites." (PMID 39399500, 2024). "In RCC, RUNX3 was upregulated in tumor tissues, compared with normal tissues according to data from The Cancer Genome Atlas (TCGA)." (PMID 38172737, 2024). "The double-sided role of RUNX3 was also reported in pancreatic ductal adenocarcinoma, both as a tumor suppressor by suppressing tumor cell proliferation, and as a tumor promoter by orchestrating a protein-secreting program supporting tumor metastasis." (PMID 38172737, 2024). "More importantly, RUNX3 was found to suppress tumor growth, migration, angiogenesis and metastasis of RCC." (PMID 38172737, 2024). "A member of the TGF-β superfamily, Runt-related transcription factor 3 (RUNX3) acts as a tumor suppressor gene and induces apoptosis." (PMID 37373414, 2023). "In particular, the R122C mutation in Runt domain has been instrumental in understanding RUNX3′s tumor suppressor roles." (PMID 36766749, 2023). "The tumor suppressor function of RUNX3 is highlighted by its transcriptional silencing from hemizygous deletion of the Runx3 gene or promoter hypermethylation." (PMID 36899853, 2023). "Poor prognosis, a tumor located in a salivary gland, and SACC recurrence all correlate highly with RUNX3 downregulation associated with DNA hypermethylation and protein mislocalization." (PMID 37373414, 2023). "RUNX3 is involved in carcinogenesis by interacting with several oncogenic signalling pathways, acting as a tumour suppressor in some tumours and as an oncogene in others." (PMID 37759525, 2023). "Although RUNX3 generally acts as a tumor suppressor, RUNX3 expression can be enhanced during the course of progression of some cancers, with this gene playing a tumor-promoting or oncogenic role." (PMID 36899846, 2023). "Curiously, it is known to act as a tumor suppressor as well as a promoter, suggesting that the effect of aberrant RUNX3 expression in cancer is context‐dependent, dependent on cancer cell types and on the tumor characters in which the cancer cells reside." (PMID 37641472, 2023). "Activation of RUNX3 played a key role in DNA damage and repair processes in response to the ionizing radiation and inhibited cell growth, thus leading to more effective tumor suppression." (PMID 37438719, 2023). "RUNX3—found to be inactivated in various cancer types, such as bladder, lung, gastric, colon, liver and breast—has been marked as a classic tumor suppressor gene in multiple studies." (PMID 36831308, 2023). "In our material we observed a trend towards impaired prognosis for patients with low nuclear and high cytoplasmic expression of RUNX3 in the tumor epithelial compartment." (PMID 36900240, 2023). "In 2017, a study was published on the key protein RUNX3, which induces T cells to leave lymphoid tissues and accumulate in peripheral and tumor tissues." (PMID 36979400, 2023). "Comparison of the resulting xenograft tumors revealed that tumor growth was significantly attenuated when RUNX3 expression was suppressed in the fibroblasts." (PMID 37641472, 2023). "Many factors account for the tumor suppressor function of RUNX3, which is reflected by its ability to suppress cancer cell proliferation after expression-restoration, and its inactivation in cancer cells." (PMID 36899853, 2023). "Given the increased RUNX3 expression in human breast CAFs, we next attempted to investigate the involvement of stromal RUNX3 in the promotion of tumor growth." (PMID 37641472, 2023). "RUNX3 was predominantly expressed in tumor infiltrating lymphocytes (TILs) and to a lesser extent in other cells." (PMID 36900240, 2023).
tumor (continued). "Given the nature of proteins targeted by RUNX3-mediated degradation in the literature, the subsequent agency of RUNX3 as tumor suppressive is established in a cancer-specific manner." (PMID 36899853, 2023). "At the same time, RUNX3 exerts its tumor suppressor function by targeting oncogenic proteins for degradation via the UPS." (PMID 36899853, 2023). "A novel tumor suppressing role for RUNX3 is shown where a direct interaction with MYC leads to disruption of MYC-MAX heterodimers and consequent degradation of the MYC oncoprotein." (PMID 37400551, 2023). "Overall, the staining results can explain the decreased xenograft tumor growth upon suppression of 544 cells' RUNX3 expression." (PMID 37641472, 2023). "Previous studies have shown that the loss of RUNX3 contributes to EMT, a crucial process related to metastasis, chemoresistance, and tumour stemness." (PMID 37759525, 2023). "The RUNX3 gene is frequently hypermethylated and epigenetically silenced in diverse solid tumors, suggesting that it plays pivotal roles in tumor suppression." (PMID 37400551, 2023). "Within a tumor core, where cells showed a range of RUNX3 and MYC expression levels, the inverse correlation of RUNX3 and MYC expression was clearly evident." (PMID 37400551, 2023). "In vitro experiments demonstrated that RUNX3 repressed tumour metastasis and invasion by upregulating E-cadherin through the miR-186/E-cadherin/EMT axis." (PMID 37759525, 2023). "The ability of RUNX3 to exhibit both tumor-suppressing and tumor-promoting activities has been associated with the R-point, a decision-making program for cell proliferation, differentiation, senescence, and apoptosis." (PMID 36899846, 2023). "A recent study revealed that after the HCC therapeutic drug’s application, sorafenib, RUNX3 suppressed VEGF expression in HCC, which was associated with reduced tumour growth." (PMID 37759525, 2023). "Then, we selected the three most effective RUNX3‐targeting shRNAs to evaluate the effects of RUNX3 suppression on the exp‐CAF 544 cells' tumor‐promoting ability in vivo." (PMID 37641472, 2023). "Transcriptional regulation by RUNX3 was also identified; a gene that functions in the suppression of tumours." (PMID 36825959, 2023). "In our material, SMAD4 and RUNX3 were weakly to moderately correlated both between and within the tumor epithelial and stromal compartments (0.3 < r < 0.6)." (PMID 36900240, 2023). "Various genes have been identified as markers to define CIMP in different tumor types, and RUNX3 is one of the five best marker genes for CIMP determination in colorectal cancers." (PMID 36831211, 2023). "In multivariate analyses, high expression of IRS1 in stromal cytoplasm, RUNX3 in tumor nucleus and stromal cytoplasm, and high expression of SMAD4 in tumor and stromal cytoplasm remained independent predictors of improved DSS." (PMID 36900240, 2023). "MUG Lucifer prim and MUG Lucifer met possessed distinct DNA methylation profiles, presenting among others a hypermethylation of RUNX3, which functions as a tumor suppressor and of miR-886, which plays an important role in cell growth regulation." (PMID 36710341, 2023).
tumor (continued). "RUNX3 becomes a key anti-oncogene which induces apoptosis among tumor cells and plays a critical part in body progression and oncogenesis." (PMID 38048186, 2023). "Crucially, among the three shRNAs used for xenograft, two of those most efficiently downregulated RUNX3 expression reduced the tumor weight significantly." (PMID 37641472, 2023). "Consistently, Ki‐67 and CD31 immunohistochemical staining of the tumor sections indicated reduction of cancer cell proliferation and microvessel formation in the tumors formed with the RUNX3‐suppressed exp‐CAFs." (PMID 37641472, 2023). "Previous studies reported that inactivation of the RUNX3 tumor-suppressor gene led to up-regulation of oncogenes expression and abnormalities in signaling pathways, which promoted the progression of various solid tumors." (PMID 36715873, 2023). "The ability of RUNX3 to act as both a tumor suppressor gene and an oncogene has indicated that the activity of this gene is dependent on cellular context." (PMID 37190031, 2023). "TFs in XIST+ and S100A4+ tumor cells were similar, particularly RUNX3, REL, STAT4, and E2F1, which regulate the EMT process." (PMID 37430270, 2023). "In support of this, experiments using a xenograft mouse model reported suppression of growth and invasiveness of MDA-MB-231 tumor cells with ectopic expression of RUNX3." (PMID 36831308, 2023). "On the other hand, RUNX3 has been shown to act as an oncogene and promote tumour development in ovarian, head and neck, and pancreatic carcinoma." (PMID 37759525, 2023). "The fact that the RUNX3-targeted proteins identified so far are transcription factors involved in oncogenic pathways tellingly illustrates RUNX3’s tumor suppressor role." (PMID 37400551, 2023). "The RUNX family of transcription factors, including RUNX1, RUNX2, and RUNX3, are key regulators of development and can function as either tumor suppressors or oncogenes in cancer." (PMID 37190015, 2023). "On the other hand, patient tumor samples with high YAP1 but low RUNX1 and RUNX3 depicted higher levels of gene signatures associated with EMT and cancer cell stemness." (PMID 36831308, 2023). "This would be a future work to further understand the mechanism of stromal RUNX3 involvement in the tumor malignancy." (PMID 37641472, 2023). "Three RUNX transcription factors, RUNX1, RUNX2, and RUNX3, along with their cofactor CBFβ, exert tumor-related functions in a context-dependent manner." (PMID 37190031, 2023). "The family of Runt-related (RUNX) genes (RUNX1, RUNX2, and RUNX3) is crucial for the different tumour types’ development and progression." (PMID 37759525, 2023). "Early studies concluded that RUNX3 functioned as a tumor suppressor and is located on human chromosome 1 at 1p36.11, a region that is missing in many types of cancers." (PMID 36518886, 2022). "RUNX3, a protein encoded by the RUNX3 gene in humans and a component of TGF-β (transforming growth factor-β), has shown tumor-suppressive effects in several cancers." (PMID 35885958, 2022). "In summary, we demonstrated the tumor-inhibiting properties of RUNX3-mediated circDYRK1A in GC via regulation of miR-889-3p/FBXO4 at the molecular, cellular and animal levels." (PMID 35272674, 2022). "RUNX3, a remarkable biomarker demonstrated in many solid malignancies, plays a main role of tumor suppression and interacts with other signaling molecules in the context of carcinogenesis in various cancer types including NSCLC." (PMID 35368900, 2022). "Collectively, RUNX3 can strongly influence anti-tumor immunity of CD4+ CTLs via direct or indirect pathways." (PMID 36231078, 2022).
tumor (continued). "The R122C mutation was shown to completely abrogate the function of RUNX3 as a tumor suppressor; while overexpression of RUNX3 slowed the proliferation of different cancer cells, overexpression of the R122C mutant failed to inhibit cell proliferation." (PMID 36429115, 2022). "RUNX family: Member of the RUNX family RUNX3, which has a tumour suppressor role in GC like many other cancers and is downregulated in cancers, can be used as a therapeutical strategy." (PMID 35565411, 2022). "Multiple logistic regression analysis showed that high expression of RUNX3 and low expression of EZH2 were significantly associated with good tumor regression (TRG grade 0/1) (P = 0.021, P = 0.016) and tumor down-staging (P = 0.014, P = 0.043)." (PMID 35280723, 2022). "In particular, we examined the effect of RUNX3 overexpression on apoptosis and inhibition of tumor migration and invasion." (PMID 36518886, 2022). "To date, expression levels of the RUNX3 gene have been assessed in a wide variety of neoplastic diseases, including AML." (PMID 36005134, 2022). "RUNX3 either influences the downstream target of tumor suppressor signaling pathways or acts as an antagonist for oncogenic pathways to exert its antitumor activity." (PMID 35898303, 2022). "Putative tumor suppressor activity of RUNX3 has been presented extensively in many solid epithelial tumors, with loss of expression favoring tumorigenesis and/or prognosis." (PMID 35368900, 2022). "RUNX3 inhibits growth of tumor cells by regulating the transcriptional growth factor β (TGF-β) and Wnt signaling pathways." (PMID 35280723, 2022). "Generally, RUNX3 is known to elicit its tumor-suppressive ability through major cancer signaling pathways including TGF-β, Wnt/β-catenin, and KRAS." (PMID 35898303, 2022). "Despite the controversy and inconsistent mechanistic evidence, the preponderance of evidence in the literature supports a role for RUNX3 in tumor biology and prognosis." (PMID 35368900, 2022). "It has recently surfaced that RUNX3 has vital roles in exerting CTL-mediated anti-tumor immune responses." (PMID 36231078, 2022). "Subsequently, RUNX3 (transcription factor) functions as a tumor suppressor protein to combat cancer initiation and metastasis through various signaling pathways." (PMID 35898303, 2022). "It is also noteworthy that some RUNX1 mutants associated with breast cancer cannot be sumoylated through PIAS1, and that in sumoylation defective mutants of RUNX3 the tumor suppressor capacity is nullified, promoting tumor growth." (PMID 35887358, 2022). "The results showed that mice that received CCRCC cells with RUNX3 overexpression had a slower rate of tumor formation and reduced tumor size and weight." (PMID 36518886, 2022). "Patients with high expression of RUNX3 showed better tumor regression response and down-staging compared with those with low expression of RUNX3 (P < 0.001, P < 0.001)." (PMID 35280723, 2022). "More specifically, RUNX3 functions as a tumor suppressor by upregulating the expression of E-cadherin, a protein that has a key function in the EMT." (PMID 36518886, 2022). "Our measurements of the expression of E-cadherin in mouse tumor tissue confirmed that E-cadherin expression and RUNX3 expression were positively correlated." (PMID 36518886, 2022). "Subsequent findings revealed that over-expression of RUNX3 restricted the growth of tumor in mice, while inhibition of circDYRK1A led to a promotion in tumor growth." (PMID 35272674, 2022). "We uncovered a novel anti-tumor role of RUNX3 in suppressing Ccl5 expression in lung-resident NK cells." (PMID 36231078, 2022). "Analysis showed that 23 out of the 25 patients with high expression of RUNX3 presented with tumor decline, whereas only 15 of the 55 patients with low expression of RUNX3 presented with tumor decline (P < 0.001)." (PMID 35280723, 2022).